PTPRC (protein tyrosine phosphatase receptor type C)
Diseases named in the same sentence as PTPRC in open-access papers (continued):
Sharing a sentence is not in itself a finding about the gene and the disease.
tumor (continued). "In the present study, we explored the effect of DNA methylation on the expression of the genes related to the non-coding RNAs but found no significant methylation of CD69, IL7R, and PTPRC in tumor tissues compared with that of normal tissues." (PMID 36032150, 2022). "Furthermore, we analyzed the expression of two cell type specific genes, the epithelial marker keratin 18 (KRT18) and the leukocyte specific marker gene CD45 (PTPRC), to differentiate between tumor epithelial cells and WBCs." (PMID 34440208, 2021). "Finally, the PPI network suggests pivotal roles for DOCK2 and PTPRC dysregulation in the progression of CRC, possibly by facilitating tumor escape from immune surveillance." (PMID 33968341, 2021). "These non-neoplastic cell populations that comprise the tumor microenvironment (TME) are identified by the expression of specific marker genes, such as PTPRC for myeloid cells and CD3E for T-cells, and contain cells captured across both datasets." (PMID 41501023, 2026). "Integrated UMAP revealed a total of 14 cell clusters comprising 5 tumor cell clusters and 9 nontumor cell clusters defined by PTPRC (CD45), marker gene expression, and copy number alterations (CNAs)." (PMID 40985888, 2025). "Patients #5, #6, and #7 (without tumor samples) showed an overlap of four genes (SORL1, PTPRC, MIR6819, and NAMPT), while #6 and #7 also shared five genes (CELF2, EDEM3, SMCHD1, RAVER1, and CXCR1)." (PMID 39001407, 2024). "We designed this circuit to implement (KRT19 OR VIM) AND-NOT PTPRC (CD45), a logical operation which could be used to distinguish epithelial or mesenchymal circulating tumor cells (CTCs) from leukocytes in blood samples." (PMID 34233007, 2021). "Notably, MED samples showed a similar epithelial cell content as in EBUS samples though with a stronger expression of markers of the tumor microenvironment (TME) (CDH5, PTPRC aka CD45, and ACTA-2) which, on the contrary, were absent in pure epithelial LNmets (EBUS samples)." (PMID 36587234, 2022).
cancer (556 papers, 2004 to 2026). A tumor composed of atypical neoplastic, often pleomorphic cells that invade other tissues. "For stroma, the marker genes used were VWF, ENG, and CDH5 (for endothelial cells), DCN, ACTA2, and FAP (for cancer-associated fibroblasts), and PTPRC, CD4, and CD163 (for leukocytes)." (PMID 33810510, 2021). "Apart from the mutation in MSH6, two further mutations in genes known to be mutated in cancer, but rarely in biliary tract carcinoma (PTPRC, MSN), were identified as “mutations of unknown relevance”." (PMID 28146430, 2017). "In pan-cancer, the expression levels of PTPRC, TLRB, PLEK, NCKAP1L, PGS18 and CLEC12A were positively correlated with GPR141." (PMID 40959105, 2025). "By using markers of specific clusters, we identified five distinct cell types, including cancer‐associated fibroblasts (CAFs) (COL1A1), endothelial cells (PECAM1), epithelial cells (CDH1), immune cells (PTPRC), and neurons (RELN)." (PMID 40038875, 2025). "Four key genes CCL2, CCR7, LY96, and PTPRC, from ClusterK1 and five genes AURKA, CDK1, CCNA2, FEN1, and PLK1 from ClusterK2, were associated with at least one type of cancer." (PMID 38872418, 2024). "Clusters were annotated based on expression of representative marker genes, as previously reported: those included EPCAM for epithelial cells, PTPRC for CD45-positive immune cells, VCAM1 for cancer-associated fibroblasts, and VWF for endothelial cells." (PMID 39122703, 2024). "Expression of EpCAM and PTPRC (CD45) are shown as positive controls for cancer cells and immune cells, respectively." (PMID 39224600, 2024). "The results show that silencing of PTPRC significantly promoted migration, invasion, and proliferative cell number of cancer cells in A375 and MEL-28 cell lines compared to controls." (PMID 37996489, 2023). "In cell sediment, PCa cells are a tiny minority, data which is supported by the very strong expression of the nucleated-blood-cell gene PTPRC in urine cells by Quek and by our data here in both PCa and non-cancer urine samples." (PMID 36765747, 2023). "CD8A, FCGR3A, and PTPRC are identified as candidate biomarkers in various cancers or important molecules in PCa patients with bone metastases." (PMID 37494663, 2023). "The general function of LCK and PTPRC is T and B cell signalling but regarding cancer, they participate in cell proliferation and tumourigenesis, respectively." (PMID 37277696, 2023). "Although these genes have known roles in cancer, only the PTPRC gene has a documented role in leukemic cells." (PMID 36139405, 2022). "We found a small cluster that expressed the marker gene for hematopoietic cells (PTPRC) and that for cancer cells (PAX8)." (PMID 35892844, 2022). "Those events occurred on pre-mRNA of 56 genes including well-known cancer-related genes PTPRC, IKBKB and HRAS, and genes coding for transcription factors ILF2, ATF2 and EYA3." (PMID 34543356, 2021). "Methylation of ITGAL and ANPEP were down-regulated, while methylation of CD69 and PTPRC were up-regulated in cancer." (PMID 34633989, 2021). "Five cancer genes mutated at greater frequency in AA LUAD tumors (MAX, ACTN2, PRKD1, PTPRC, STK11) remained significant after accounting for mutation burden and age at diagnosis." (PMID 32952607, 2020). "The PTPRC+ droplets were easily excluded from sorting, preventing possible contamination of the sorted cancer cells with undesirable background cells." (PMID 27189161, 2016). "Briefly, this method is based on defining an immune-normalizing gene set (INGS) per cancer type, which is defined empirically using an expression measurement found by correlation with the expression of the gene PTPRC." (PMID 26384298, 2015).
cancer (continued). "Finally, the experiment verified that the model genes LTB and PTTG1 were relatively highly expressed in cancer tissues, while PTPRC was relatively highly expressed in paracancerous tissues." (PMID 37671160, 2023). "Also, we found that PTPRC overexpression activated oxidative phosphorylation, inhibited cancer cell epithelial-mesenchymal transition, and mediated cell cycle arrest, resulting in cancer progression suppression." (PMID 36405010, 2022). "Down-regulation of PTPRC has been reported in several cancer types." (PMID 33968341, 2021). "Total leukocyte infiltration in syngeneic models by CD45 (PTPRC) expression from RNA-Seq had a similar trend as did cytolytic activity, another indicator of cancer immunity, which was also highest in CT26 and 4T1 and lowest in B16F10 and RENCA among the solid tumor models." (PMID 31898484, 2020). "In addition to known cancer driver genes such as ERBB2 (6% of cases), NRAS (3%), MET (3%), PIK3CA (1%), AKT2 (1%), TSC1 (1%), and ERBB4 (1%), several putative cancer genes were identified, such as PTPRC, SYNE2, GRIN2A, and CDH10." (PMID 24576404, 2014). "While analyzing multiple cancer disorders, we found highly variable expression among genes implicated in cancer: EEF1A1, GNAS, NPM1, PIM1, and RHOA are known oncogenes; H3F3A, PTPRC, SMARCB1, and B2M are possible oncogenes; and CASP8, JAK1, and PRKAR1A are known tumor suppressor genes." (PMID 34174938, 2021). "The integrative analysis identified PROX1+ LEC subsets, JAM2+ BECs, COL1A1+ stromal cells, PTPRC+ leukocytes, including MZB1+ plasmablasts, KRT19+ cancer cells, and MKI67+-proliferating cells." (PMID 41249124, 2025). "We performed correlation analysis of these six genes (PTPRC, TLR8, PLEK, NCKAP1L, RGS18 and CLEC12A) with GPR141 in pan-cancer." (PMID 40959105, 2025). "The results showed that PTPRC, TLR8, PLEK, NCKAP1L, RGS18 and CLEC12A displayed strong correlation with GPR141 in most cancer types." (PMID 40959105, 2025). "In particular, we noted that cancer-related genes including METTL1, ALKBH2, PSPH, PTPRC, and TRIP13 contributed the most to the identification, which indicated the great biological interpretability of our model." (PMID 38243719, 2024). "Specifically, the TCGA datasets were integrated to evaluate the correlations of LATS2 expression with the four specific immune cell gene markers (PTPRC, BCL6, NRP1, and THBD) in 33 cancer types." (PMID 34699318, 2021). "The subnetwork involves an interesting combination of the downregulation of the cancer gene EGFR and the amplification of a group of genes involved in T-cell receptor signaling (PTPRC, CD247, and ARPC5)." (PMID 30978274, 2019). "Furthermore, LATS2 expression was positively correlated with the expression of PTPRC, BCL6, NRP1, and THBD in almost all cancers in the TCGA database." (PMID 34699318, 2021). "We identified genes for which ASEs were observed in both the Afro-Caribbean cohort and the Jurkat cells expressing Tax or HBZ, including cancer genes EIF4A2, IKBKB, LZTR1, STAT6 (for Tax); CARS, MDM2, IKZF1 (for HBZ); and EWSR1, MUTYH, and PTPRC (for both Tax and HBZ)." (PMID 34543356, 2021). "For example, ADT levels of EPCAM on cancer/epithelial cells (c0, c4, c8, c14 and c15), CD31 (PECAM1) and CD34 on endothelial cells (c7 and c9), CD146 (MCAM) on perivascular cells (c11), CD90 (THY1) and CD34 on CAFs (c13) and CD45 (PTPRC) on immune cells (c3, c5 and c12)." (PMID 33971952, 2021). "In the process of module analysis and characteristic molecular screening, we selected two characteristic modules and 10 characteristic molecules (PTPRC, CD2, CD69, IRF8, CCR7, CCL5, il2rb, CXCL10, CCR5, TBX21), which could be used as biomarkers of cancer stem-like cells for GIST patients." (PMID 34925310, 2021).
cancer (continued). "In contrast, the expression of PTPRC and PTPRG were decreased in cancer tissue compared with normal tissue." (PMID 30126387, 2018). "Whether these signals are common across multiple cancer types is not known, but several of these receptor-ligand pairs (CXCR6-CXCL16, CTLA-4-CD86, LGALs9-CD44/PTPRC) have been shown to play roles in cancer modulation." (PMID 35493454, 2022).
infection (533 papers, 2004 to 2026). The state of being infected such as from the introduction of a foreign agent such as serum, vaccine, antigenic substance or organism. "In the guinea pigs, PTPRC expression appeared to increase after exposure to Mtb and decrease after the infection persisted for a longer period of time." (PMID 26818387, 2016). "Examination of the ontologies enriched in this set of up-regulated genes showed genes known to play a role in infection processes, including NR3C1, PTPRC, SFRS1, SFRS5, SMAD3, C3 and DDX58." (PMID 22363497, 2012). "These variants were found in inflammasome genes (NLRP1/3 and CASP1), genes mediating inflammasome inactivation via auto- and mitophagy (RIPK2 and MEFV), and genes involved in the response to infection with DNA viruses (POLR3A, DHX58, and IFIH1) and type-1 interferons (TYK2 and PTPRC)." (PMID 37626706, 2023). "Likewise, B cell differentiation genes (BCL10, CD72, FOS, PTPRC, SH3BP5, PTPN6, etc.)were also downregulated throughout the infection, correlating with the drop of B cell numbers at D8." (PMID 37146079, 2023). "These variants were found in inflammasome genes (NLRP1/3, CASP1), genes mediating inflammasome inactivation via auto and mitophagy (RIPK2, MEFV), and genes involved in response to infection with DNA viruses (POLR3A, DHX58, IFIH1) and to type-1 interferons (TYK2, PTPRC)." (PMID 31235738, 2019). "In addition, except for 4 of the regulatory genes (IRF4, JAK1, NFATC4 and STAT6), many of the other genes in this pathway were only transiently expressed at 2 (IL4R and PTPRC) or 4 and/or 8 (IL13, IL4 and CEBPB) weeks post-infection." (PMID 23448601, 2013). "In addition, CD3+ T cells temporally increased at 5 dpi and there was no change in PTPRC+ B cells throughout the infection period." (PMID 36457995, 2022).
cardiovascular diseases (8 papers, 2010 to 2025). "This multifunctional regulatory mechanism highlights the importance of PTPRC as a potential therapeutic target for cardiovascular diseases, offering new avenues for future research aimed at combating AS." (PMID 39805933, 2025).
infectious disease (7 papers, 2017 to 2025). A disorder directly resulting from the presence and activity of a microbial, viral, or parasitic agent in humans. "Mouse studies revealed that CD45 deficiency as well as hyperactivity have major consequences for cells of the hematopoietic lineage, and also the decades of studies on human materials established PTPRC as an important immunomodulatory gene with impact on autoimmune and infectious diseases." (PMID 36755664, 2022).
PTPRC also shares sentences with these, for which no sentence is quoted: glioma (76 papers); Stroke (52); glioblastoma (37); Obesity (32); breast tumors (30); Arthritis (26); influenza (25); pulmonary fibrosis (25); acute myeloid leukemia (22); multiple myeloma (22); sarcoma (22); Splenomegaly (21); T-cell lymphoma (21); hematological malignancies (19); anemia (17); lymphopenia (17); myeloid leukemia (17); myocarditis (17); brain tumors (16); adenocarcinoma (15); ischemia (15); HIV-1 infection (14); pancreatitis (14); Ewing sarcoma (13); pneumonia (13); inflammation (12); ischemic stroke (12); liver cancer (12); Lymphadenopathy (12); prostate tumors (12).
A further 560 diseases each share a sentence with PTPRC in 11 papers or fewer.